NOS1AP (nitric oxide synthase 1 adaptor protein)
Description:
Adapter protein involved in neuronal nitric-oxide (NO) synthesis regulation via its association with nNOS/NOS1. The complex formed with NOS1 and synapsins is necessary for specific NO and synapsin functions at a presynaptic level. Mediates an indirect interaction between NOS1 and RASD1 leading to enhance the ability of NOS1 to activate RASD1. Competes with DLG4 for interaction with NOS1, possibly affecting NOS1 activity by regulating the interaction between NOS1 and DLG4 (By similarity). In kidney podocytes, plays a role in podosomes and filopodia formation through CDC42 activation.
Synonyms: CAPON; KIAA0464; 6330408P19Rik; NPHS22
Tractability: Antibody: its Gene Ontology location is reachable by antibodies, with medium confidence. PROTAC: ubiquitination databases record sites on it; its protein half-life has been measured.
Safety:
Unwanted effects reported when the protein is acted on. In parentheses: how it was acted on, where the effect was seen, and who reports it.
cardiovascular and all-cause mortality (source: ClinPGx)
hypoglycemia (source: ClinPGx)
QT-interval shortening effect (source: ClinPGx)
QTc interval prolongation (source: ClinPGx)
QTc prolongation (source: ClinPGx)
ventricular arrhythmia and QT prolongation (source: ClinPGx)
Gene: Protein-coding gene on chromosome 1 (162,069,691 to 162,370,475, forward strand). Ensembl gene ENSG00000198929.
Subcellular location: Cell projection, filopodium; Cell projection, podosome
Subcellular location (Human Protein Atlas): Nucleoplasm; Vesicles
Gene Ontology:
Molecular function: protein binding; nitric-oxide synthase binding; nitric-oxide synthase regulator activity; signaling adaptor activity
Biological process: postsynaptic actin cytoskeleton organization; regulation of heart rate by chemical signal; regulation of ventricular cardiac muscle cell membrane repolarization; nitric oxide biosynthetic process; positive regulation of membrane repolarization during ventricular cardiac muscle cell action potential; positive regulation of potassium ion transmembrane transport; regulation of calcium ion transmembrane transport via high voltage-gated calcium channel; regulation of cardiac muscle cell action potential; regulation of nitric oxide biosynthetic process
Cellular component: glutamatergic synapse; caveola; cytosol; mitochondrion; nuclear membrane; nucleus; perinuclear region of cytoplasm; sarcolemma; sarcoplasmic reticulum membrane; T-tubule; Z disc; filopodium; podosome
Genetic constraint (gnomAD): Loss-of-function variants: 16 observed, 49.09 expected, observed/expected ratio (o/e) 0.33, 90% interval 0.22 to 0.5. The upper end of that interval is the gene's LOEUF score, 0.5, which puts it in group 2 of 6, group 1 being the genes least tolerant of losing a copy. Missense variants: 497 observed, 638.59 expected, observed/expected ratio (o/e) 0.78, 90% interval 0.72 to 0.84. Synonymous variants: 259 observed, 269.23 expected, observed/expected ratio (o/e) 0.96, 90% interval 0.87 to 1.07.
Homologues: Orthologues: chimpanzee NOS1AP (100% identical), mouse Nos1ap (95% identical), rat Nos1ap (94% identical), guinea pig NOS1AP (84% identical), zebrafish nos1apa (66% identical), tropical clawed frog nos1ap (66% identical), Caenorhabditis elegans dyc-1 (42% identical), Drosophila melanogaster CG42673 (23% identical), Drosophila melanogaster Dab (17% identical), Caenorhabditis elegans dab-1 (11% identical), Drosophila melanogaster numb (11% identical), Caenorhabditis elegans num-1 (10% identical), and 4 more. Paralogues in human: NUMB (15% identical), DAB2 (14% identical), MAPK8IP2 (13% identical), MAPK8IP1 (13% identical), NUMBL (13% identical), DAB1 (13% identical), LDLRAP1 (12% identical), FAM43A (11% identical), FAM43B (9% identical), GULP1 (6% identical), C1orf226 (5% identical).
Diseases named in the same sentence as NOS1AP in open-access papers:
NOS1AP is named in the same sentence as 71 diseases in open-access papers, as found by Europe PMC text mining. Sharing a sentence is not in itself a finding about the gene and the disease. The quoted sentences say what the papers report.
schizophrenia (28 papers, 2005 to 2025). A major psychotic disorder characterized by abnormalities in the perception or expression of reality. "NOS1AP is 1 of more than 1000 candidate genes identified as putatively associated with the development of schizophrenia (according to the SZGene database)." (PMID 40508138, 2025). "The NOS1AP gene is also 1 among more than 1000 genes that are presumed to be associated with the development of schizophrenia." (PMID 40508138, 2025). "From another point of view, healthy individuals with schizophrenia-associated SNVs in NOS1AP demonstrated significantly greater activation of the dorsolateral prefrontal cortex when performing a task of working memory." (PMID 40508138, 2025). "In this paper, we report results of a study on possible involvement of three variants of the NOS1AP gene in MetS pathogenesis in 489 Caucasian patients with schizophrenia." (PMID 38540239, 2024). "On the other hand, NOS1AP polymorphisms play a part in the etiology of mental illnesses, such as schizophrenia and post-traumatic stress disorder." (PMID 38540239, 2024). "The aim of the investigation was to study polymorphic variants of the NOS1AP gene as possible markers of MetS in patients with schizophrenia." (PMID 38540239, 2024). "The aim of this work was to investigate polymorphic variants of the NOS1AP gene as possible markers of MetS in patients with schizophrenia." (PMID 38540239, 2024). "In this study, we examined associations of three polymorphic variants of the nitric oxide synthase 1 adapter protein (NOS1AP) gene with MetS in schizophrenia." (PMID 38540239, 2024). "For example, genetic variants of NOS1AP have been associated with multiple mental disorder phenotypes and higher cortical and hippocampal expression was observed in patients with schizophrenia and depression." (PMID 34455393, 2021). "This system, and NOS1AP in particular, has been linked to different mental disorders, including schizophrenia, depression, and posttraumatic stress disorder." (PMID 34455393, 2021). "Sensorimotor gating, operationalized by PPI of the ASR is impaired in schizophrenia and other mental disorders and NOS1AP variants affecting PPI and startle have been identified." (PMID 34455393, 2021). "This pathway has been previously implicated in psychiatric conditions such as schizophrenia and anxiety through one of its key effectors, the “Nitric Oxide Synthase 1 Adaptor Protein” (NOS1AP)." (PMID 30655502, 2019). "The authors studied the role of polymorphisms of genes NOS1 and NOS1AP in schizophrenia development." (PMID 26029110, 2015). "The nos1ap gene is linked to diseases including schizophrenia, post-traumatic stress disorder and depression, autism, sudden cardiac death and long QT syndromes and diabetes." (PMID 25221472, 2014). "In agreement, genetic association study revealed that single nucleotide polymorphisms (SNP) in NOS1AP were associated with schizophrenia." (PMID 19538708, 2009). "Moreover, the expression level of NOS1AP was found to correlate with single-nucleotide variations (SNVs), which have been shown to be associated with schizophrenia in Canadian families." (PMID 40508138, 2025). "Moreover, serum metabolome analysis demonstrates sufficient sensitivity and specificity to provide insights into NOS1AP-rs12742393 genotype-associated metabolic profiles, supporting a network-based approach to understanding schizophrenia susceptibility." (PMID 40863167, 2025). "This region contains a large number of genes, including nitric oxide synthase 1 adaptor protein (NOS1AP), which may be regarded as a candidate positional gene for susceptibility to metabolic disorders and schizophrenia." (PMID 38540239, 2024). "NOS1AP is a protein encoded by a schizophrenia susceptibility gene." (PMID 26869880, 2016). "Recent studies reported evidence of a significant association between NOS1AP and schizophrenia." (PMID 21886582, 2011).
schizophrenia (continued). "We show that NOS1AP interacts with α-synuclein, allowing us to suggest that this protein may be implicated in the development of synucleinopathies and that its aggregation may explain the relationship between Parkinson’s disease and schizophrenia." (PMID 36012368, 2022). "Indeed GWAS have implicated NOS1AP and nNOS in schizophrenia." (PMID 25221472, 2014). "Increased levels of NOS1AP mRNA, as well as the corresponding protein, have been reported in patients with schizophrenia." (PMID 40508138, 2025). "Proteins such as DISC1, CRMP1, NOS1AP, and others have been identified with altered expression and aggregation patterns in schizophrenia, linking protein abnormalities to disease pathology." (PMID 41217487, 2025). "Overexpression of NOS1AP was found in rat models for nervous system injury as well as in schizophrenia patients." (PMID 36012368, 2022). "Of note, one study showed a ∼100-fold increase of NOS1AP expression in the dorsolateral prefrontal cortex of patients with schizophrenia." (PMID 34455393, 2021). "Through virus-mediated NOS1AP overexpression in the dorsal hippocampus of mice we recapitulated alterations in dendritic spine morphology also observed e.g. in patients with schizophrenia and mood disorders." (PMID 34455393, 2021). "We have previously characterized a functional SNP in gene NOS1AP under the chromosome 1 peak that exhibits strong linkage disequilibrium to a narrow schizophrenia phenotype in this sample." (PMID 29529098, 2018). "Nitric oxide synthase 1 adaptor protein (NOS1AP), a risk gene for schizophrenia, encodes proteins that are upregulated in the dorsolateral prefrontal cortex (DLPFC) of individuals with schizophrenia." (PMID 26869880, 2016). "Our group and others reported that mRNA and protein levels of NOS1AP isoforms are increased in postmortem samples from the DLPFC of subjects with schizophrenia." (PMID 26869880, 2016). "To elucidate the effects of NOS1AP overexpression observed in individuals with schizophrenia, we investigated changes in actin dynamics and spine development when a long (NOS1AP-L) or short (NOS1AP-S) isoform of NOS1AP is overexpressed." (PMID 26869880, 2016). "Increased NOS1AP-L and NOS1AP-S protein expression in the DLPFC of individuals with schizophrenia coupled with alterations in neurodevelopmental processes regulated by NOS1AP isoforms suggest that NOS1AP isoforms play a role in cognitive function." (PMID 26869880, 2016). "For association of polymorphisms of gene encoding carboxyl-terminal PDZ ligand of neuronal nitric oxide synthase (NOS1AP) with schizophrenia, few investigations have been carried out." (PMID 26029110, 2015). "All the exons of NOS1AP were directly sequenced in a large subset of subjects (n = 280), including patients with schizophrenia (n = 72), ASD (n = 81) and OCD (n = 34), and in healthy volunteers (n = 93)." (PMID 20602773, 2010). "The gene encoding carboxyl-terminal PDZ ligand of neuronal nitric oxide synthase (NOS1AP) is located on chromosome 1q23.3, a candidate region for schizophrenia, autism spectrum disorders (ASD) and obsessive-compulsive disorder (OCD)." (PMID 20602773, 2010). "Investigating the functional role of NOS1AP in schizophrenia development is challenging in humans." (PMID 40508138, 2025). "This led us to speculate that NOS1AP overproduction in schizophrenia may lead to the formation of NOS1AP aggregates." (PMID 40508138, 2025). "NOS1AP overproduction described in patients with schizophrenia is in good agreement with this hypothesis because it may prevent the interaction between NOS1 and NMDAR and thus decrease the activity of the receptor." (PMID 40508138, 2025). "Based on this, we wanted to test whether an overproduction and aggregation of the NOS1AP protein occurs in schizophrenia and, in particular, under NMDAR inhibition in vivo and in vitro." (PMID 40508138, 2025). "An increase in NOS1AP production has been described in patients with schizophrenia." (PMID 40508138, 2025).
schizophrenia (continued). "Studies searching for associations of NOS1AP gene variants with MetS in schizophrenia patients have not been conducted previously." (PMID 38540239, 2024). "Our results indicate that the NOS1AP gene may be involved in the pathogenesis of MetS in schizophrenia." (PMID 38540239, 2024). "Our results suggest that in patients with schizophrenia, NOS1AP may be involved in MetS pathophysiology." (PMID 38540239, 2024). "SNPs in the promoter region of NOS1AP for instance are correlated to schizophrenia." (PMID 36352324, 2023). "The NOS1AP protein, which is linked to schizophrenia development, can form detergent-resistant non-amyloid aggregates when overproduced." (PMID 36012368, 2022). "Recently we found increased NOS1AP mRNA in hippocampus of schizophrenia patients (in preparation)." (PMID 34455393, 2021). "It has been specifically suggested that nNOS-NOS1AP interaction could be a therapeutic target in schizophrenia, while NOS1AP has emerged as a highly significant associated gene in cardiovascular conditions." (PMID 28360833, 2017). "In the present study, we link NOS1AP to the regulation of the actin cytoskeleton, further implicating NOS1AP to the neurodevelopmental hypothesis of schizophrenia." (PMID 26869880, 2016). "Conditions of NMDAR hypoactivity, as thought to occur in schizophrenia, might be exacerbated by NOS1AP." (PMID 25221472, 2014). "Based on the evidence of NOS1AP gene involvement in schizophrenia, the relevance for dendrite branching, and its role in mediating NMDAR-PSD-95 signaling, further studies suggested that its overexpression in dorsolateral PFC of patients may result in disruption of NMDAR functions." (PMID 35883465, 2022). "Our findings suggest that identifying potential pathways and molecular targets affected by NOS1AP isoforms, as we have done in this study, may prove important for understanding the cognitive deficits observed in schizophrenia and can guide future therapeutic studies." (PMID 26869880, 2016). "In the same study, the authors showed that D-serine reduced the expression, in male rats, of nitric oxide synthase 1 adaptor protein (NOS1AP), which has been found overexpressed in the cortex of patients with schizophrenia." (PMID 35883465, 2022). "For example, elevated NOS1AP mRNA and protein was found in blood and the dorsolateral prefrontal cortex (DLPFC) of patients with schizophrenia." (PMID 34455393, 2021). "The SNP rs12140791 is located in NOS1AP (MIM: 605551) gene which is essential for brain development and function and of potential relevance to schizophrenia." (PMID 31024629, 2019). "As NOS1AP is involved in signal transmission in the system of N-methyl-d-aspartate-receptors (NMDAR), it is a potentiallyimportant component in the etiology of schizophrenia." (PMID 32111088, 2020). "In addition, transcription of nitric oxide synthase 1 (neuronal) adaptor protein (NOS1AP) that is also termed CAPON, was upregulated both in schizophrenia and bipolar disorder." (PMID 19538708, 2009). "Importantly, PSD-95 has been suggested as a critical synaptic mediator of schizophrenia-related molecular consequences and our previous study has shown that integrity of the NOS1AP/nNOS/PSD-95 complex is critical for the effect of NOS1AP on dendritic growth and spine plasticity." (PMID 34455393, 2021). "Furthermore, NOS1AP plays a role in the signal transduction cascade through N-methyl-D-aspartate (NMDA) receptors, a dysfunction of which is the basis of the glutamatergic hypothesis of schizophrenia." (PMID 38540239, 2024).
depression (9 papers, 2017 to 2023). "Moreover, NOS1AP variants have been associated with symptom severity, and depression and anxiety symptoms in posttraumatic stress disorder (PTSD)." (PMID 34455393, 2021). "Nevertheless, they suggest that the NOS1AP SNV rs386231 may increase susceptibility to severe depression in patients with PTSD and thereby increase a risk forsuicide." (PMID 32111088, 2020). "Of note, downregulation of NOS1AP in prefrontal cortex was shown to normalize depression-related behaviours in mice exposed to chronic mild stress." (PMID 34455393, 2021). "NOS1AP was previously linked to depression and depression phenotypes, but not specifically within the hippocampus." (PMID 34455393, 2021). "Increased NOS1AP immunoreactivity in the DLPFC and the anterior cingulate cortex, was described in patients with major depressive disorder." (PMID 34455393, 2021).
Anxiety (7 papers, 2017 to 2026). Intense feelings of nervousness, tension, or panic often arise in response to interpersonal stresses. "For example, inhibition of NOS1AP/nNOS interactions normalized anxiety related behaviours caused by chronic mild stress." (PMID 34455393, 2021). "Other cross-disorder phenotypes such as anxiety, startle, prepulse inhibition of the startle response, anhedonia, and spatial reference memory, were not affected, implying a more specific association of hippocampal NOS1AP in mental disorder-related behaviours." (PMID 34455393, 2021). "Consistent with this lack of clinical association, in the present study overexpression of NOS1AP throughout the dorsal hippocampus did not affect anxiety-related behaviours." (PMID 34455393, 2021). "Experimental models suggest that NOS1AP may mediate the actions of NMDA-driven nNOS function for example in excitotoxic conditions such as neonatal hypoxia and anxiety induced by chronic mild stress." (PMID 28360833, 2017). "Recently N-(2-carboxyacetyl)-D-valine-methyl ester, also known as ZLc-002-1, a valine-based analog of the C-terminus of NOS1AP, has been proposed as a competitive inhibitor for nNOS PDZ pocket ligands and has shown efficacy against anxiety induced by chronic mild stress." (PMID 28360833, 2017). "To date, despite preclinical evidence revealing that genetic or pharmacological disruption of nNOS/NOS1AP interactions targeting an intermediate region of the dentate gyrus (and parts of CA3) has anxiolytic effects [13,], there is no study linking NOS1AP to anxiety in humans." (PMID 34455393, 2021).